SMARCB1 (SWI/SNF related BAF chromatin remodeling complex subunit B1)
Diseases named in the same sentence as SMARCB1 in open-access papers (continued):
Sharing a sentence is not in itself a finding about the gene and the disease.
atypical teratoid rhabdoid tumor (51 papers, 2013 to 2026). Atypical teratoid rhabdoid tumor (ATRT) is a highly malignant central nervous system (CNS) rhabdoid tumor (RT) found almost exclusively in children. "HERV-K env RNA expression is upregulated in patients with atypical teratoid rhabdoid tumor (AT/RT) by deletion or mutation of integrase interactor 1 (SMARCB1)." (PMID 38540701, 2024). "Mutations in SMARCA4 or SMARCB1 (which encodes the core subunit BAF47) can give rise to highly aggressive pediatric brain tumors such as atypical teratoid/rhabdoid tumors (ATRTs) and medulloblastomas." (PMID 38427725, 2024). "SMARCB1-deficient tumors like atypical teratoid rhabdoid tumor (ATRT) are considered mutationally quiet; however, there have been a few isolated reports of using atezolizumab/pembrolizumab/nivolumab in this disease population with a minimal response." (PMID 38140246, 2023). "SMARCB1 inactivation is strongly associated with aggressive atypical teratoid rhabdoid tumors (ATRT) in children." (PMID 36831595, 2023). "This cancer is driven by the loss of SMARCB1, a tumor suppressor seen in a number of primarily rare childhood cancers (e.g., rhabdoid tumor of the kidney and atypical teratoid rhabdoid tumor)." (PMID 35806102, 2022). "Atypical teratoid/rhabdoid tumor (ATRT) is a highly malignant central nervous system tumor characterized by loss of SMARCB1/INI1 protein expression." (PMID 35501487, 2022). "Atypical teratoid/rhabdoid tumors (ATRTs) are the most common type of SMARCB1/INI1-deficient tumors in the central nervous system (CNS), although these aggressive pediatric brain tumors are very rare." (PMID 35804041, 2022). "Atypical teratoid/rhabdoid tumor (AT/RT) is a highly malignant brain tumor in infants that is characterized by loss of nuclear expression of SMARCB1 or SMARCA4 proteins." (PMID 36127323, 2022). "The MIR17HG gene encodes a cluster of six miRNAs that have been shown to increase sensitivity to palbociclib in atypical teratoid rhabdoid tumors (ATRTs), a fatal pediatric malignancy of the central neural system caused by SMARCB1 deficiency." (PMID 36498861, 2022). "Atypical teratoid rhabdoid tumors (ATRTs) of the central nervous system are characterized by SMARCB1 loss, a key component of SWI/SNF chromatin remodeling complex." (PMID 34439268, 2021). "Although SMARCA4 mutations are less penetrant for atypical teratoid rhabdoid tumor than SMARCB1, SCCOHT was exclusively observed in patients constitutionally carrying the deleterious variant of SMARCA4." (PMID 33907931, 2021). "Atypical teratoid rhabdoid tumors (AT/RTs) are rare pediatric brain tumors characterized by bialleic loss of the SMARCB1 tumor suppressor gene." (PMID 26557502, 2015). "BACKGROUND: Atypical teratoid/rhabdoid tumors (AT/RT) are aggressive pediatric CNS malignancies characterized by SMARCB1 loss, which leads to the dysregulated expression of Enhancer of Zeste Homolog 2 (EZH2), a key catalytic component of the Polycomb Repressive Complex 2 (PRC2)." (PMID 41915306, 2026). "Atypical teratoid rhabdoid tumor (ATRT) is a highly aggressive but genetically simple pediatric central nervous system tumor, defined by biallelic inactivation of the chromatin regulator SMARCB1 with remarkably few other cooperating mutations." (PMID 41408661, 2025). "Both atypical teratoid rhabdoid tumor (AT/RT) models were based on a Rosa26-creERT2-driven KO of Smarcb1 at embryonal day 6.5." (PMID 41381884, 2026). "Atypical teratoid rhabdoid tumors (AT/RT) are characterized by mutations and subsequent inactivation of SMARCB1 (INI1, hSNF5), a predilection for very young children and an unfavorable outcome." (PMID 27228363, 2016). "Inactivating mutations in SMARCB1 confer an oncogenic dependency on EZH2 in atypical teratoid rhabdoid tumors (ATRTs), but the underlying mechanism has not been fully elucidated." (PMID 39472584, 2024).
atypical teratoid rhabdoid tumor (continued). "With the development of gene sequencing technology, an increasing number of studies have confirmed that the tumor suppressor gene INI1/SMARCB1, which is ubiquitously expressed in normal tissue, is completely lost in MRTs and atypical teratoid/rhabdoid tumors (ATRTs)." (PMID 33456348, 2021). "This underlines the importance of regular screening for early detection of central nervous system rhabdoid tumors in patients with r22 and deletion of 22q13 (although not involving mutations of the SMARCB1 gene)." (PMID 34777208, 2021). "Mutations of SMARCB1 were described in atypical teratoid rhabdoid tumors and to date have not been associated with the pathogenesis of medulloblastoma." (PMID 29971034, 2018). "Atypical Teratoid Rhabdoid Tumor (ATRT) is an embryonal CNS tumor of early childhood with a poor prognosis, characterized by biallelic inactivation of SMARCB1 (or, less commonly, SMARCA4), a core component of the SWI/SNF chromatin remodeling complex." (PMID 41408661, 2025). "At relapse both patient’s disease was reclassified as atypical teratoid rhabdoid tumor (ATRT) based on loss of INI-1, presence of SMARCB1 alterations, and methylation profiling results." (PMID 38639853, 2024). "We investigated the contribution of SMARCB1 to changes in chromatin activity in Malignant rhabdoid tumors of kidney (MRTK) and atypical teratoid rhabdoid tumor (ATRT)." (PMID 34071089, 2021). "SMARCB1 expression is completely absent in both PDC and atypical teratoid/rhabdoid tumor (AT/RT), and TBXT and cytokeratin immunoexpressions of PDC are diffuse and strong, and combining SMARCB1 with TBXT staining helps to distinguish PDC from AT/RT." (PMID 36520826, 2022).
sarcoma (50 papers, 2013 to 2025). A usually aggressive malignant neoplasm of the soft tissue or bone. "On that occasion the final histopathological results were discussed, confirming the diagnosis of SMARCB1-deficient mediastinal sarcoma." (PMID 40364921, 2025). "In SMARCB1-deficient sarcomas, several clinical trials have reported variable success rates with checkpoint blockade as monotherapy or as combination therapy." (PMID 39125735, 2024). "EZH2 inhibition in particular has been biologically and clinically viable, having shown efficacy in SMARCB1-deficient sarcomas." (PMID 39125735, 2024). "In our opinion Claudin-4 is helpful in the differentiation of SMARCB1 (INI1) - deficient carcinoma and sarcoma." (PMID 35864317, 2022). "B cell lymphomas often have activating mutations in EZH2, and some subtypes of sarcomas have mutations in SWI-SNF subunits SMARCB1 (BAF47) or SMARCA4 (BRG1)." (PMID 35852858, 2022). "Converging recent data support that SMARCB1 loss favors anti-tumor immunogenicity, at least in certain subtypes of SMARCB1-deficient sarcomas and carcinomas." (PMID 35327458, 2022). "Although SMARCB1/INI1-deficient tumors are predominantly sarcomas, this is a diverse group of tumors with mixed phenotypes, which can often make the diagnosis challenging." (PMID 33796273, 2020). "We located 25 cases of adult SMARCB1/INI1-deficient sarcomas that were described in 18 reports 42,50,93–108." (PMID 33796273, 2020). "The only phenotype ascribed to these animals are soft tissue tumors, mainly sarcomas, that are thought to develop upon additional loss-of-function of the second Smarcb1 allele." (PMID 31273213, 2019). "Malignant rhabdoid tumours (MRTs) are lethal paediatric sarcomas, characterized by a deficiency in the SMARCB1 subunit of the SWI/SNF chromatin-remodelling complex, which is involved in tumour development." (PMID 30423915, 2018). "SMARCB1/INI1-deficient mice develop rapidly aggressive undifferentiated sarcomas, implying a cancer-related function." (PMID 24286138, 2013). "The tumor response rate of tazemetostat in epitheliod sarcomas with loss of INI1/SMARCB1 was 15%." (PMID 39941804, 2025). "This review will discuss the current evidence for using immunotherapy in SMARCB1-deficient sarcoma." (PMID 35327458, 2022). "Assessing the dose-response effects of ponatinib in the panel of 17 cell lines, consisting of five SMARCB1-deficient cell lines (A204, G402, G401, BT12, and CHLA226) and 12 wild-type sarcoma cell lines, confirmed that cells with SMARCB1 deficiency were sensitive to this TKI." (PMID 27783942, 2016). "Examples of antibodies serving as surrogate markers of sarcoma-specific genetic aberrations, e.g., fusions, amplifications, and point mutations, include SS18-SSX or SSX, TFE3, SMARCB1, BCOR, MDM2, DDIT3, and PAX3." (PMID 40526340, 2025). "Despite numerous efforts to elucidate the genetics of ES, the only recurrent alteration detected to date in this very rare and aggressive sarcoma is the functional inactivation of SMARCB1." (PMID 36078034, 2022). "Two patients each with refractory, metastatic, sarcoma NOS harboring a SMARCB1 deletion and BRAFV600E had a durable partial response to tazemetostat, an EZH2 inhibitor and a rapid response to vemurafenib and trametinib, respectively." (PMID 35705558, 2022). "In view of its overlapping features with other sarcomas, certain immunohistochemical antibody markers, including cytokeratins and vascular markers, along with INI1/SMARCB1 are essential for its diagnosis." (PMID 34514569, 2022). "Recently, the new and first-in-human EZH2 inhibitor, tazemetostat, showed an encouraging anti-tumor activity in SMARCB1-deleted sarcomas." (PMID 32532153, 2020). "Our cohort also included two sarcomas with VIM–KMT2A fusions, each harboring concurrent mutations in CTNNB1, SMARCB1, and ARID1A and characterized histologically by sheets of spindle-to-round blue cells." (PMID 32461620, 2020).
sarcoma (continued). "The presence of TLS in SMARCB1-defective sarcoma and its association with response to immunotherapy have not been studied yet." (PMID 35327458, 2022). "Evaluation of our synaptophysin results with those reported in the literature in sarcomas/mesenchymal neoplasms showed that synaptophysin is most frequently expressed in CCS, DSRCT, ES, and neoplasms deficient for SMARCB1 and SMARCA4." (PMID 34350470, 2021). "However, how exactly SMARCB1 loss leads to cGAS/STING activation, and whether this is also the case in other SMARCB1-defective carcinomas or sarcomas, remains to be elucidated." (PMID 35327458, 2022). "In summary, primary adult sellar SMARCB1/INI1-deficient tumors have similar DNA methylation profiles with the pediatric ATRT-MYC subgroup, however, primary adult sellar SMARCB1/INI1-deficient tumors are different from bona fide (P)ES, PDC, and other CNS brain entities and sarcomas." (PMID 35804041, 2022). "The interaction between SMARCB1 and NSD1 is essential for the deposition of H3K36me2 in the genome, which is a marker for better prognosis in sarcoma." (PMID 36589746, 2022). "The use of ICIs is a promising therapeutic strategy, and therapeutic efficacy has already been reported in SMARCB1-negative sarcomas." (PMID 36732357, 2023). "Similarly, the expression levels of SWI/SNF-related genes, such as SMARCB1, SMARCA2, and SMARCA5-AS1 also seemed to be differentially expressed in MFS/US sarcomas." (PMID 37185612, 2023). "Clinical benefits of immune checkpoint inhibitor therapy in SMARCB1-negative sarcoma have been reported in several clinical trials and individual case reports." (PMID 35327458, 2022). "More recently, Forrest and colleagues investigated PD-L1 expression in 30 SMARCB1-negative sarcomas, including ES and anaplastic chordoma." (PMID 35327458, 2022). "In a retrospective analysis of 1479 intrathoracic malignant neoplasms using immunohistochemistry for INI1 (SMARCB1) on tissue micro arrays (TMA) and a search through our hospital sarcoma database, we identified in total nine intrathoracic, INI1 deficient cases (n = 9)." (PMID 35864317, 2022). "In mice, whereas homozygous inactivation leads to early embryonic lethality, heterozygous loss promotes the development of undifferentiated or poorly differentiated sarcomas consistent with MRT observed in infants, highlighting the central role of SMARCB1 in this disease." (PMID 35327458, 2022). "Inclusion of other SWI/SNF immunomarkers, such as ARID1A, in the differential diagnostic workup of poorly differentiated sarcoma not fitting well-known subtypes, such as SMARCB1 and SMARCA4-deficient sarcomas, is recommended." (PMID 35125107, 2022).
renal medullary carcinoma (45 papers, 2013 to 2026). "We report the case of a woman with metastatic SMARCB1-deficient renal medullary carcinoma who developed acute hypoxic respiratory failure shortly after receiving combination gemcitabine and carboplatin." (PMID 41959950, 2026). "Histologically, collecting duct carcinoma is a diagnosis that requires diligent exclusion from another epithelial tumor, urothelial carcinoma, SMARCB1-deficient renal medullary carcinoma (RMC), FH-deficient RCC, and high-grade RCC and is vanishingly rare." (PMID 40361453, 2025). "Renal medullary carcinoma (RMC) is a rare aggressive kidney cancer characterized by the loss of SMARCB1 tumor suppressor and predominantly affects young male adults with SCT and other hemoglobinopathies." (PMID 40758858, 2025). "RCC tumors have demonstrated an elevated LAG3 expression, with notable upregulation observed in histologic variants such as papillary RCC, SMARCB1-deficient renal medullary carcinoma, and translocation RCC." (PMID 39858107, 2025). "Rare histologic subtypes, such as SMARCB1-deficient renal medullary carcinoma, translocation RCC, and collecting duct carcinoma, often express distinct biomarkers that are less prevalent in ccRCC." (PMID 39858107, 2025). "The molecularly defined renal carcinomas include TFE3-rearranged RCC, TFEB-altered RCC, ELOC-mutated RCC, FH-deficient and SDH-deficient RCC, ALK-rearranged RCC, and SMARCB1-deficient renal medullary carcinomas." (PMID 38235567, 2024). "Renal medullary cancer has been reclassified as SMARCB1-deficient renal medullary carcinoma, as indicated by multiple sources." (PMID 38765391, 2024). "In one study, an adult patient with recurrent SMARCB1-loss renal medullary carcinoma had complete response to nivolumab lasting greater than 9 months despite low TMB." (PMID 38217014, 2024). "The molecular mechanisms involved in the development of SMARCB1-deficient renal medullary carcinomas (RMCs) remain to be characterised." (PMID 37236926, 2023). "Renal medullary carcinoma (RMC) is an aggressive tumour driven by bi-allelic loss of SMARCB1 and tightly associated with sickle cell trait." (PMID 37236926, 2023). "In the 2022 edition of the WHO classification for RCC, this class of renal medullary carcinoma (RMC) with mutations in the SMARCB1 gene is classified as a new molecular category called SMARCB1-deficient RMC." (PMID 37367052, 2023). "Third, the BEVAEL trial using bevacizumab plus gemcitabine and platinum in CDC and SMARCB1-deficient renal medullary carcinoma (RMC) reported an ORR of 39% with an mOS of 11 months (n = 26 of 34)." (PMID 36359359, 2022). "Renal medullary carcinoma (RMC) is a rare entity with poor prognosis bearing inactivating genomic alterations in SMARCB1/INI1 resulting in the loss of expression of INI1 and occurring in young patients with sickle cell trait or sickle cell disease." (PMID 35198580, 2022). "Renal medullary carcinoma present a frequent loss INI1 (SMARCB1) implicated in the chromatin remodeling complex." (PMID 32260578, 2020). "In addition to immunohistochemistry for INI1 expression loss, other molecular tests can be used to diagnose renal medullary carcinoma with SMARCB1 deficiency." (PMID 40777608, 2025). "Moreover, assessment of INI1 loss aids the differential diagnosis between SMARCB1-deficient renal medullary carcinoma and high-grade invasive urothelial carcinoma or collecting duct carcinoma." (PMID 37999735, 2024). "Moreover, it has been shown that SMARCB1-mutated renal medullary carcinoma are also dependent on the ubiquitin/proteasome system." (PMID 33941852, 2021). "SMARCB1 loss has been linked to the activation of several oncogenic signalling pathways (e.g., hedgehog or Wnt) and the development of malignant tumours such as renal medullary carcinoma." (PMID 33941852, 2021).
renal medullary carcinoma (continued). "Immunohistochemical loss of the SMARCB1/INI1 protein expression has been described in myoepithelial carcinomas and renal medullary carcinomas, in a subset of malignant peripheral nerve sheath tumors and of extraskeletal myxoid chondrosarcomas as well as in ES of both distal and proximal type." (PMID 23691400, 2013). "Moreover, the lack of effective systemic immunotherapies for rare histologic subtypes such as SMARCB1-deficient renal medullary carcinoma and collecting duct RCC represents an opportunity to explore the role of TIL therapy and other novel adoptive immune agents in these populations." (PMID 39858107, 2025). "Renal medullary carcinoma (RMC), recently renamed in WHO guidelines as SMARCB1-deficient renal medullary carcinoma, is a rare malignancy that is significantly associated with hemoglobinopathies, particularly sickle cell trait and sickle cell disease." (PMID 39858107, 2025). "SMARCB1-deficient renal medullary carcinoma (RMC) is a rare and aggressive kidney cancer defined by the loss of SMARCB1 tumor suppressor and primarily affecting adolescents and young adults with sickle hemoglobinopathies." (PMID 40951353, 2025). "Renal medullary carcinoma is a rare undifferentiated tumor of the kidney associated with sickle cell trait and characterized by INI1 (SMARCB1) loss." (PMID 39833894, 2025). "EZH2 inhibitors have demonstrated promise for RCCs with INI1 (SMARCB1) loss, such as renal medullary carcinoma." (PMID 39858107, 2025). "Renal medullary carcinomas (RMC) are aggressive tumors of the kidneys, characterized by a loss of SMARCB1." (PMID 36291828, 2022). "Renal medullary carcinomas (RMC) are rare aggressive tumors of the kidneys, characterized by a loss of SMARCB1." (PMID 36291828, 2022). "In the rare RCC category, collecting duct carcinoma (CDC) harbors mutations in NF2, SETD2, SMARCB1, FH, and CDKN2A genes while renal medullary carcinoma is distinctively characterized by loss of SMARCB1/INI1 tumor suppressor protein." (PMID 32575429, 2020). "The remaining IHC profile of ALK‐rearranged RCC is variable, but includes reactivity for PAX8 and vimentin, and retained FH and INI1, the last two being useful in differentiating it from FH‐deficient RCC and SMARCB1‐deficient renal medullary carcinoma, respectively." (PMID 41384711, 2026). "SMARCB1-deficient renal medullary carcinoma (RMC) is a rare form of non-clear cell renal carcinoma with an abysmal prognosis." (PMID 41497945, 2025). "In addition, SMARCB1 mutations are found in SMARCB1-deficient renal medullary carcinoma and are accompanied by loss of SMARCB1 protein (INI1) expression on IHC." (PMID 37999735, 2024). "Loss of SMARCB1/INI1 expression is characteristically found in atypical teratoid/rhabdoid tumor of the central nervous system, renal rhabdoid tumors (pediatric and adult), and renal medullary carcinoma." (PMID 35583077, 2022). "Studies have shown that in cases of renal medullary carcinoma, there may be hemizygous loss and translocation of SMARCB1, homozygous loss, or, in some cases, no structural or copy number alteration despite the protein loss." (PMID 40777608, 2025).